OTUD1 (OTU deubiquitinase 1)
Diseases named in the same sentence as OTUD1 in open-access papers (continued):
Sharing a sentence is not in itself a finding about the gene and the disease.
cancer (continued). "Thus, OTUD1 could be considered as a therapeutic target for curing these cancers." (PMID 31467488, 2019). "OTUD1 was subsequently identified as a potent negative regulator of the TGF-β signaling pathway, a strong inducer of EMT and cancer cell stemness." (PMID 29235476, 2017). "Combined, the in vitro and in vivo evidence in this study elucidates critical functions of OTUD1 in the termination of TGF-β/SMAD-induced metastatic activation, indicating that OTUD1 restricts the EMT and cancer stem cell traits during metastasis." (PMID 29235476, 2017). "We focused on these two because both shRNAs target OTUD1, an OTU domain family member with a largely unexploited function in cancer." (PMID 29235476, 2017). "In addition, we investigated whether OTUD1 transcription is downregulated in cancer." (PMID 29235476, 2017). "OTUD1 is a deubiquitinating enzyme that is not well studied and mainly limited in immune and cancer fields." (PMID 37498303, 2023). "Herein, we made efforts in examining the hypothesized regulatory effects of OTUD1 on the NSCLC cell growth dynamics and chemoresistance, and clarifying the potential anti-cancer network of OTUD1/YAP1/SOX9/SPP1." (PMID 36182943, 2022). "As OTUD1 regulates MCL1 protein levels, we tested whether OTUD1 influences the toxicity of a BH3 mimetic in cancer cells." (PMID 31467488, 2019). "According to bioinformatics analysis, we found that OTUD1 is a negative prognostic factor for multiple cancers and that it could be considered as a therapeutic target for curing these cancers." (PMID 31467488, 2019). "Interestingly, depletion of OTUD1 did not affect SKOV3 cell growth, implying that OTUD1 probably contributes to cancer progression through its effect on OSCS." (PMID 38351029, 2024).
infection (6 papers, 2018 to 2023). The state of being infected such as from the introduction of a foreign agent such as serum, vaccine, antigenic substance or organism. "Knockout mice for OTUD1 produce high levels of antiviral cytokines and are more resistant to infection with RNA viruses." (PMID 37228615, 2023). "The levels of IFNβ mRNA in Otud1-/- MEFs were much higher than that in Otud1+/+ MEFs during infection of SeV, or VSV, or H1N1." (PMID 29734366, 2018). "Consistent with the results obtained by intraperitoneal VSV injection, Otud1-/- mice with VSV intranasal infection had lower VSV loads at day 3 than did Otud1+/+ mice." (PMID 29734366, 2018). "We demonstrate that at the early stage of infection, RNA virus infection rapidly activates OTUD1 expression by inducing OTUD1 mRNA in a NF-κB-dependent manner." (PMID 29734366, 2018). "AAV9 infection was successful and showed increased OTUD1 expression in heart tissues of mice." (PMID 37153745, 2023). "Moreover, the downregulation course of IFNβ mRNA within 12 hr infection with RNA viruses was blocked in Otud1-/- primary liver cells, as well as in Otud1-/- MEFs." (PMID 29734366, 2018). "Upon infection with Sendai virus (SeV), a single-stranded RNA virus, Otud1−/−-MEFs and -BMDMs showed reduced expression of IRF3-target genes as compared to Otud1+/+-cells." (PMID 35941131, 2022). "However, DNA viruses HSV did not upregulate OTUD1 mRNA expression in 2fTGH or MEFs at the early stage of infection." (PMID 29734366, 2018).
cardiovascular diseases (1 paper, 2024). "Recent evidence suggested the OTUD1 significance in cardiovascular diseases." (PMID 39118286, 2024).
OTUD1 also shares sentences with these, for which no sentence is quoted: colon cancer (2 papers); Hepatitis (2); ischemia (2); liver cancer (2); multiple myeloma (2); myocardial infarction (2); Acute hepatitis (1); adenocarcinoma (1); arteriosclerosis (1); cardiomyopathy (1); Cerebellar atrophy (1); chronic periodontitis (1); Crohn disease (1); dementia (1); Encephalopathy (1); glioblastoma (1); Hashimoto thyroiditis (1); hypertrophy (1); infectious disease (1); latent infection (1); lupus erythematosus (1); melanoma (1); multiple sclerosis (1); ulcerative colitis (1).